RNU6-1211P (RNA, U6 small nuclear 1211, pseudogene)
Gene: Small nuclear RNA gene on chromosome 1 (232,700,204 to 232,700,308, forward strand). Ensembl gene ENSG00000238382.
Homologues: Orthologues: chimpanzee U6 (98% identical), macaque U6 (97% identical), mouse Gm22140 (56% identical), pig U6 (53% identical). Paralogues in human: RNU6-181P (76% identical), RNU6-869P (76% identical), RNU6-1024P (75% identical), RNU6-1260P (75% identical), RNU6-144P (75% identical), RNU6-16P (75% identical), RNU6-19P (75% identical), RNU6-317P (75% identical), RNU6-536P (75% identical), RNU6-61P (75% identical), RNU6-820P (75% identical), RNU6-1065P (74% identical), and 1286 more.